KRT82 (keratin 82)
Description:
Structural component of intermediate filaments in the hair follicle. As a type II hair keratin, forms obligate heterodimers with type I hair keratins that assemble into keratin intermediate filaments. Expressed specifically in cuticle-forming cells of the hair shaft during the anagen phase, where it contributes to the formation and structural integrity of the hair cuticle.
Synonyms: KRTHB2; Hb-2; HB2
Tractability: PROTAC: its protein half-life has been measured.
Gene: Protein-coding gene on chromosome 12 (52,393,931 to 52,406,335, reverse strand). Ensembl gene ENSG00000161850.
Subcellular location: Cytoplasm
Pathways (Reactome):
Developmental Biology: Formation of the cornified envelope; Keratinization
Gene Ontology:
Molecular function: protein binding; structural molecule activity; structural constituent of skin epidermis
Biological process: intermediate filament organization; keratinization
Cellular component: cytoplasm; keratin filament; cytosol
Genetic constraint (gnomAD): Loss-of-function variants: 41 observed, 47.05 expected, observed/expected ratio (o/e) 0.87, 90% interval 0.68 to 1.13. The upper end of that interval is the gene's LOEUF score, 1.13, which puts it in group 4 of 6, group 1 being the genes least tolerant of losing a copy. Missense variants: 693 observed, 687.99 expected, observed/expected ratio (o/e) 1.01, 90% interval 0.95 to 1.07. Synonymous variants: 294 observed, 285.48 expected, observed/expected ratio (o/e) 1.03, 90% interval 0.94 to 1.13.
Homologues: Orthologues: chimpanzee KRT82 (99% identical), macaque KRT82 (97% identical), pig KRT82 (89% identical), dog KRT82 (88% identical), rat Krt82 (87% identical), mouse Krt82 (86% identical), guinea pig KRT82 (84% identical), rabbit KRT82 (68% identical). Paralogues in human: KRT84 (59% identical), KRT85 (57% identical), KRT81 (57% identical), KRT83 (55% identical), KRT86 (55% identical), KRT5 (49% identical), KRT6A (48% identical), KRT6C (48% identical), KRT6B (47% identical), KRT75 (47% identical), KRT73 (46% identical), KRT3 (46% identical), and 56 more.
Diseases named in the same sentence as KRT82 in open-access papers:
KRT82 is named in the same sentence as 4 diseases in open-access papers, as found by Europe PMC text mining. Sharing a sentence is not in itself a finding about the gene and the disease. The quoted sentences say what the papers report.
alopecia areata (2 papers, 2022 to 2025). Loss of scalp and body hair involving microscopically inflammatory patchy areas. "KRT82 is identified as an Alopecia Areata risk gene with rare damaging variants in 51 heterozygous Alopecia Areata individuals (6.01%), achieving genome-wide significance (p = 2.18E−07)." (PMID 35145093, 2022). "In addition, relevant studies suggested that KRT82, being a risk gene for alopecia areata, is also associated with hair fiber fineness." (PMID 40941372, 2025). "KRT82 encodes a hair-specific type II keratin that is exclusively expressed in the hair shaft cuticle during anagen phase, and its expression is decreased in Alopecia Areata patient skin and hair follicles." (PMID 35145093, 2022).
endometrial cancer (2 papers, 2012 to 2023). Primary or metastatic malignant neoplasm involving the endometrium (mucous membrane that lines the endometrial cavity). "In addition, keratin 82 (KRT82) mutations have been shown to be prevalent in gastric, colorectal, and endometrial cancers." (PMID 36824011, 2023).
alopecia (1 paper, 2022). Hair loss usually from the scalp. "Although other keratin levels were affected in this animal model, the decrease in KRT82 and association with cyclical alopecia substantiates an important role for KRT82 in hair follicle biology, and underscores the impact of LOF and damaging variants in AA pathogenesis." (PMID 35145093, 2022).
KRT82 also shares sentences with these, for which no sentence is quoted: cancer (1 paper).